PCGF5 (polycomb group ring finger 5)
Description:
Component of a Polycomb group (PcG) multiprotein PRC1-like complex, a complex class required to maintain the transcriptionally repressive state of many genes, including Hox genes, throughout development. PcG PRC1 complex acts via chromatin remodeling and modification of histones; it mediates monoubiquitination of histone H2A 'Lys-119', rendering chromatin heritably changed in its expressibility. Within the PRC1-like complex, regulates RNF2 ubiquitin ligase activity. Plays a redundant role with PCGF3 as part of a PRC1-like complex that mediates monoubiquitination of histone H2A 'Lys-119' on the X chromosome and is required for normal silencing of one copy of the X chromosome in XX females (By similarity).
Synonyms: RNF159; MGC16202
Tractability: PROTAC: its protein half-life has been measured.
Gene: Protein-coding gene on chromosome 10 (91,162,339 to 91,284,337, forward strand). Ensembl gene ENSG00000180628.
Subcellular location: Nucleus; Nucleus, nucleoplasm
Subcellular location (Human Protein Atlas): Nucleoplasm
Pathways (Reactome):
Gene expression (Transcription): RUNX1 interacts with co-factors whose precise effect on RUNX1 targets is not known
Gene Ontology:
Molecular function: protein binding; histone H2AK119 ubiquitin ligase activity
Biological process: positive regulation of transcription by RNA polymerase II; heterochromatin formation; positive regulation of DNA-templated transcription; random inactivation of X chromosome; regulation of transcription by RNA polymerase II; regulation of gene expression
Cellular component: centrosome; nucleoplasm; nucleus; PcG protein complex; chromatin; PRC1 complex; X chromosome
Genetic constraint (gnomAD): Loss-of-function variants: 7 observed, 27.43 expected, observed/expected ratio (o/e) 0.26, 90% interval 0.14 to 0.48. The upper end of that interval is the gene's LOEUF score, 0.48, which puts it in group 2 of 6, group 1 being the genes least tolerant of losing a copy. Missense variants: 118 observed, 211.72 expected, observed/expected ratio (o/e) 0.56, 90% interval 0.48 to 0.65. Synonymous variants: 60 observed, 69.06 expected, observed/expected ratio (o/e) 0.87, 90% interval 0.7 to 1.08.
Homologues: Orthologues: chimpanzee PCGF5 (99% identical), guinea pig PCGF5 (98% identical), rabbit PCGF5 (98% identical), mouse Pcgf5 (96% identical), macaque PCGF5 (94% identical), dog PCGF5 (93% identical), rat Pcgf5 (84% identical), tropical clawed frog pcgf5 (75% identical), zebrafish pcgf5b (74% identical), Drosophila melanogaster Su(z)2 (26% identical), Drosophila melanogaster Psc (22% identical). Paralogues in human: PCGF3 (39% identical), BMI1 (32% identical), PCGF2 (31% identical), PCGF6 (31% identical), PCGF1 (30% identical), RNF2 (21% identical), RING1 (21% identical).
Diseases named in the same sentence as PCGF5 in open-access papers:
PCGF5 is named in the same sentence as 10 diseases in open-access papers, as found by Europe PMC text mining. Sharing a sentence is not in itself a finding about the gene and the disease. The quoted sentences say what the papers report.
breast carcinoma (1 paper, 2025). "However, PCGF5 is not prognostic in breast cancer according to the Human Protein Atlas." (PMID 40867231, 2025).
esophageal adenocarcinoma (1 paper, 2016). A malignant tumor with glandular differentiation arising predominantly from Barrett mucosa in the lower third of the esophagus. "In contrast, overexpression of PCGF5 has been reported for esophageal adenocarcinoma, indicating that PCR1.5 may activate or suppress tumorigenesis, depending on the cellular context." (PMID 27322685, 2016).
Myeloma (1 paper, 2024). "Myeloma cells with NLRC5 mutations and overexpression of selected genes including TNFRSF10D, NCR3LG1, ULBP1, PVR, and PCGF5 were sensitive to NK cells." (PMID 38410372, 2024). "Myeloma cells with TRAF3 and WHSC1 mutations and overexpression of TNFRSF10D, NCR3LG1, ULBP1, PVR, and PCGF5 were tolerance to NK cells." (PMID 38410372, 2024).
Parkinson disease (1 paper, 2023). A progressive degenerative disorder of the central nervous system characterized by loss of dopamine producing neurons in the substantia nigra and the presence of Lewy bodies in the substantia nigra and locus coeruleus. "BANF1, PCGF5, WDR5, RYBP and BRD2 are related to the immune process of Parkinson’s disease and can predict the occurrence of Parkinson’s disease, which is expected to become a new target for the diagnosis and treatment of Parkinson’s disease." (PMID 36813848, 2023).
triple-negative breast carcinoma (1 paper, 2025). An invasive breast carcinoma which is negative for expression of estrogen receptor (ER), progesterone receptor (PR), and human epidermal growth factor receptor 2 (HER2). "PCGF5 is also a component of the PRC1 (non-canonical PRC1) complex: overall, PRC1 components can interact with oestrogen receptor alpha (ERα), and the factor FOXA1 in ER-positive breast cancer cells, as well as with BRD4 in triple-negative breast cancer cells." (PMID 40867231, 2025).
infection (5 papers, 2017 to 2024). The state of being infected such as from the introduction of a foreign agent such as serum, vaccine, antigenic substance or organism. "TRP120 interacts with an array of host proteins such as immunoglobulin light-chain lambda and polycomb group ring finger 5, involved in immune and cellular signaling, metabolism, and protein synthesis/degradation to control over the immune response and facilitate infection." (PMID 29641592, 2018). "At both 1 and 2 days p.i., only PCGF5 knockdown increased E. chaffeensis infection significantly, but the knockdown of 25 (71%) proteins decreased the infection significantly at 1 day p.i., and the knockdown of 26 (74%) proteins negatively affected infection significantly at 2 days p.i.." (PMID 28553621, 2017). "Numerous host proteins were upregulated upon infection with Francisella, ranging from immune-related proteins to metabolic enzymes, including notably IRG1, MARCO, Rilpl2, C3, PcgF5, MT1, TRAF1, GBP2 and Fas." (PMID 38565565, 2024). "We previously reported that TRP120 moonlights as a HECT E3 Ub ligase that ubiquitinates host cell transcription and fate regulators (PCGF5 and FBW7) to promote infection." (PMID 34451426, 2021). "We previously showed that the transcription repressor, polycomb group ring finger protein 5 (PCGF5), is a substrate of TRP120 Ub ligase activity, resulting in PCGF5 degradation and enhanced infection." (PMID 34451426, 2021).
tumor (5 papers, 2021 to 2025). "Moreover, Pcgf3 has previously been implicated in the regulation of tumour cell proliferation, whereas Pcgf5 and Pcgf3/5 were dispensable for embryonic stem cell self-renewal." (PMID 39933923, 2025). "The seven genes comprising the HMR model (SUZ12, KAT2A, AURKA, BUB1, SUV39H2, UTY, and PCGF5) are critically involved in epigenetic modification, tumor progression, supporting their prognostic value in MM." (PMID 40949882, 2025). "Furthermore, AUTS2 and PCGF5 may (de)regulate ONECUT2 activity via chromatin modifications in the tumor cells." (PMID 38474011, 2024). "Six genes CCSER2, AGAP11, IFIT2, PAPSS2, PCGF5, and NUDT9P1 were observed to have potential NB tumor suppressor activity since their low expression was associated with poor survival even after correction for confounding by other prognostic factors (MYCN status, age at diagnosis, stage of disease)." (PMID 37046696, 2023).
cancer (1 paper, 2021). A tumor composed of atypical neoplastic, often pleomorphic cells that invade other tissues. "Recent studies have revealed that the PCGF family of proteins (PCGF1 (Nspc1), PCGF2 (Mel-18), PCGF3, PCGF4 (Bmi1), PCGF5 and PCGF6 is robustly elevated in diverse human cancers and promotes cancer progression." (PMID 34148069, 2021).
PCGF5 also shares sentences with these, for which no sentence is quoted: colon adenocarcinoma (1 paper); insulinoma (1).